INS (insulin)
Diseases named in the same sentence as INS in open-access papers (continued):
Sharing a sentence is not in itself a finding about the gene and the disease.
endothelial dysfunction (continued). "Likewise, endothelial dysfunction has been suggested to be detected very early in the life of insulin resistant subjects despite a lack of significant structural changes, indicated by a thickening of the intima-media layer." (PMID 24139427, 2013). "Moreover, we demonstrated that this endothelial dysfunction due to impaired acetylcholine-dependent vasodilation was accompanied by endothelial insulin resistance and SMC hyper contractility in response to both phenylephrine and insulin." (PMID 21635764, 2011). "Insulin therapy could be clinically considered useful to restore normal maternal and fetal glycemia when dietary therapy is insufficient; however, its usefulness in avoiding endothelial dysfunction is still unclear." (PMID 37370929, 2023). "However, the increased insulin after test meal loading may not have played an important role in the acute induction of endothelial dysfunction in our patients." (PMID 23777506, 2013). "Since vitamin C completely reversed insulin-induced endothelial dysfunction without affecting the vascular endothelium-independent response, they speculated that oxidative stress was one of the intermediate steps in insulin-induced endothelial dysfunction." (PMID 20334663, 2010). "Its ability to induce endothelial dysfunction was further confirmed by the authors, supporting the view that ApoC-III dose-dependently attenuated insulin-stimulated eNOS activity without affecting its expression." (PMID 33407555, 2021). "These patients also had higher IMT-CC, HOMA-IR, and fasting insulin levels than those with newly diagnosed T2DM and non-severe endothelial dysfunction (p < 0.05 for all comparisons)." (PMID 31963378, 2020). "Patients with established T2DM and severe endothelial dysfunction (i.e., FMD < 2%) had higher serum MG levels, IMT-CC, HOMA-IR and fasting insulin levels than those with newly diagnosed T2DM and non-severe endothelial dysfunction (i.e., FMD ≥ 2%) (all p < 0.05)." (PMID 31963378, 2020). "Nevertheless, it has been suggested that insulin does not exert a direct effect on ATBF, rather insulin might be an important mediator, possibly acting via sympathetic activation or endothelial dysfunction." (PMID 28346464, 2017). "We previously demonstrated the marked hepatosteatosis and endothelial dysfunction in hepatocyte-specific ERK2 knockout mice (LE2KO) with a high-fat/high-sucrose diet (HFHSD), but detailed metabolic changes and the characteristics in insulin-sensitive organs were not tested." (PMID 35955653, 2022). "In addition, although insulin and endothelial dysfunction may alter the PWV, insulin levels and endothelial function biomarkers were not measured in the present study." (PMID 34960045, 2021). "An antidiabetic treatment with either insulin or metformin in ZDF rats inhibits the development of hypoadiponectinemia and downregulation of APPL1 in mesenteric resistance arteries, but is not able to improve adiponectin induced vasodilation and endothelial dysfunction." (PMID 23497197, 2013).
polycystic ovary syndrome (572 papers, 2007 to 2026). A disorder that manifests as multiple cysts on the ovaries. "Ovarian DNA hypomethylation in polycystic ovary syndrome rats regulates key genes associated with inflammation, insulin signaling, and glucose metabolism." (PMID 41490440, 2026). "Elevated insulin levels can amplify LH stimulation, increasing androgen secretion and causing hyperandrogenemia." (PMID 40008316, 2025). "In women with polycystic ovary syndrome, high levels of testosterone in adipose tissue are associated with disruptions to insulin action and adipokine secretion, markers of adipose dysfunction." (PMID 39856754, 2025). "Several women achieved pregnancy via treatment with insulin sensitizers and less need for insulin, probably linked to a specific insulin-resistant phenotype, as also demonstrated by the prevalence of polycystic ovary syndrome in these patients." (PMID 39479521, 2024). "Chronically high levels of insulin in the bloodstream cause the ovaries to produce more androgens, which contributes to polycystic ovarian syndrome which was 8.1% in the current study." (PMID 39628749, 2024). "Early postnatal overfeeding induced defects at critical nodes of the insulin signaling pathway in skeletal muscle, which was associated with reduced glucose uptake in the presence of hyperandrogenemia." (PMID 37371678, 2023). "Metformin, an insulin sensitisation agent, has also been reported to have a modest effect on weight loss and is used in women with polycystic ovary syndrome (PCOS)." (PMID 37700375, 2023). "Weight loss not only improves metabolic abnormalities and insulin sensitivity, but also improves hyperandrogenemia and promotes follicle development." (PMID 36248406, 2022). "Excessive insulin level is not only a potential cause of hyperandrogenemia but also one of the high-risk factors leading to metabolic syndromes among those with PCOS." (PMID 36276838, 2022). "In fact, different authors consider that resistance to insulin and elevated levels of androgen would be the main causes of polycystic ovarian syndrome." (PMID 35412268, 2022). "For example, it was associated with reduced fasting glucose-insulin ratio and increased homeostasis model assessment and body mass index in the polycystic ovary syndrome group." (PMID 32514254, 2020). "Genetic variants in melatonin receptor have been linked to increased risk of developing polycystic ovary syndrome, to impairments in insulin secretion, and to increased fasting glucose levels." (PMID 30147722, 2018). "This alteration in insulin sensitivity is also an associated and common factor in the polycystic ovarian syndrome." (PMID 27672393, 2016). "In addition, the Mediterranean Diet was associated with enhanced insulin sensitivity, which is particularly beneficial for women suffering from polycystic ovary syndrome (PCOS) or obesity-related infertility." (PMID 41305556, 2025). "Studies performed on pregnant animals show that testosterone hyper-exposure during pregnancy might cause polycystic ovaries, high sebum, LH concentrations and insulin resistance in the offspring." (PMID 40869238, 2025). "High insulin levels may be a predisposing characteristic for other points of hormonal dysregulation through actions such as bolstering the hyperandrogenemia induced by genetic susceptibilities or environmental perturbations." (PMID 40013621, 2025). "The significance of insulin balance in the reproductive system is also crucial, with recent research indicating that insulin plays a role in worsening symptoms and complications associated with polycystic ovary syndrome." (PMID 40725728, 2025). "Despite, in humans, some insulin-resistant states like the end of pregnancy or polycystic ovarian syndrome being associated with higher estrogen concentration, estrogens have been claimed to have serial protective effects in insulin-target tissues and other organs in post-menopause women." (PMID 38539988, 2024).
polycystic ovary syndrome (continued). "Moreover, in PCOS, increased levels of circulating insulin contribute to hyperandrogenism, which causes a derangement in folliculogenesis, thereby contributing to polycystic ovary morphogenesis and higher than normal AMH." (PMID 38549135, 2024). "Lipid indices have been highly associated with impaired insulin metabolism and hyperandrogenemia." (PMID 36837921, 2023). "A meta-analysis study on lifestyle interventions for polycystic ovary syndrome patients revealed that such interventions could improve metabolic parameters like weight loss and insulin resistance, positively impacting infertility treatment." (PMID 37152275, 2023). "IGF1 is one of the genes related to the insulin signaling pathway, and it’s up-regulation may cause polycystic ovary syndrome and endometrial cancer." (PMID 34054819, 2021). "Zinc may be associated with the development of polycystic ovary syndrome and its long-term metabolic complications through participation in glucose metabolism and the synthesis, secretion, and signaling of insulin." (PMID 34203167, 2021). "We conclude that prenatal exposure to testosterone disrupts pancreatic insulin secretion in response to glucose and that in this setting further hyperandrogenemia may predispose to lower insulin sensitivity." (PMID 31941959, 2020). "Indeed, in humans, polycystic ovary syndrome (PCOS) is associated with altered insulin sensitivity and hormonal imbalance." (PMID 33330722, 2020). "All treatments that reduce serum insulin levels, whether weight loss due to lifestyle changes, bariatric surgery, metformin or thiazolidinedione, significantly diminish anovulation and hyperandrogenemia." (PMID 29972435, 2018). "Vitamin D and insulin play an important role in susceptibility to polycystic ovary syndrome (PCOS), and therefore vitamin D receptor (VDR), parathyroid hormone (PTH), and insulin receptor (INSR) gene variants might be involved in the pathogenesis of PCOS." (PMID 27141540, 2015). "Polycystic ovary syndrome (PCOS) causes a hormonal imbalance with an increased amount of androgen, luteinizing hormone, and insulin." (PMID 36751233, 2023). "Some human diseases, such as early follicular atresia and ovulation dysfunction caused by polycystic ovary syndrome (PCOS), are also usually accompanied by a decrease in the capability of insulin-mediated glucose uptake of ovary tissues (GCs and endometrium)." (PMID 35563579, 2022). "A study of women with polycystic ovarian syndrome showed decreased breast growth in pregnancy was associated with decreased exclusive and any breastfeeding, being more common in older women, and women with higher first trimester BMI, and higher fasting insulin concentrations in this patient group." (PMID 35405936, 2022). "Among them, D-chiro-inositol (DCI) is commonly used in clinical practice for polycystic ovary syndrome (PCOS), a specific clinical condition in which a profound insulin resistance state underlies the physiopathological mechanisms of the syndrome." (PMID 33020399, 2020). "Myo-Inositol (MI), a natural compound with insulin-sensitizing properties, has been associated with improved ovarian function in both women with polycystic ovary syndrome (PCOS) and poor responders." (PMID 32932604, 2020). "Several studies have pointed out that metformin is an effective treatment for anovulation in women with polycystic ovary syndrome and leads to a relevant reduction in the insulin levels, and metformin isolated or associated with other drugs might lead to ovulation return reducing the PCOS features." (PMID 29430464, 2017). "PPARγ Pro12Ala polymorphism is associated with insulin sensitivity and BMI in patients with polycystic ovary syndrome (PCOS)." (PMID 27483259, 2016). "Subparameter assessments revealed that insulin-regulated aminopeptidase levels were even lower in insulin-resistant polycystic ovary syndrome patients (p = 0.001)." (PMID 41719418, 2026).
polycystic ovary syndrome (continued). "The extract of sage was shown the body mass index and systolic blood pressure of patients with polycystic ovary syndrome and improve the insulin resistance index." (PMID 40842497, 2025). "The acute symptoms include excessive weight gain, insulin insensitivity, hyperandrogenism, hormonal imbalances, numerous polycystic ovaries, irregular uterine bleeding, anovulation, infertility, and many other identifying factors." (PMID 41509115, 2025). "In states of androgen excess, such as PCOS, this shift can attenuate hyperandrogenemia and improve menstrual cyclicity and ovulatory function, with concurrent gains in insulin sensitivity." (PMID 41470894, 2025). "It has been shown that myo-inositol, when administered as a dietary supplement to women with polycystic ovary syndrome (PCOS), improves insulin sensitivity and menstrual regularity while causing fewer gastrointestinal complaints compared to metformin." (PMID 40700266, 2025). "Lower IL-22 may act as a biomarker of improved metabolic health rather than the direct cause, as seen in T2DM and Polycystic Ovary Syndrome (PCOS) where moderate exercise reduces inflammation and improves insulin sensitivity." (PMID 41585797, 2025). "Exercise specifically improves insulin sensitivity and reduces hyperandrogenemia through mechanisms including enhanced glucose disposal, SHBG upregulation, and visceral adiposity reduction." (PMID 40941484, 2025). "A recent study showed that exogenous supplementation with NAC alleviates 5α-dihydrotestosterone- and insulin-induced uterine and placental ferroptosis in polycystic ovary syndrome-like pregnant rats." (PMID 39037665, 2025). "In women with polycystic ovary syndrome (PCOS), elevated chemerin expression in granulosa-lutein cells is associated with reduced insulin sensitivity due to impaired IRS1/2 and Akt phosphorylation." (PMID 41457200, 2025). "Decreased free testosterone indicates alleviated hyperandrogenemia, partly attributed to improved insulin sensitivity." (PMID 41141268, 2025). "By way of illustration, the established role of inositols in insulin signaling underscores the importance of employing myo-inositol and D-chiro-inositol isomers as insulin sensitizers in the management of polycystic ovary syndrome." (PMID 40283032, 2025). "Epigallocatechin gallate and resveratrol modulate peroxisome proliferator-activated receptor gamma activity, improving insulin sensitivity crucial for hormonal balance in polycystic ovary syndrome." (PMID 41141268, 2025). "In this study, hyperandrogenemia in sheep mothers lowered insulin sensitivity in female offspring compared to sheep born to mothers with normal levels of androgens." (PMID 40076815, 2025). "It is likely that impaired insulin action and hyperandrogenemia are a part of the vicious circle observed in CAH." (PMID 39240753, 2025). "The study aimed to determine the impact of quercetin on adiponectin-mediated insulin sensitivity in patients with polycystic ovary syndrome (PCOS)." (PMID 39858545, 2025). "Insulin has another mechanism which leads to hyperandrogenemia, i.e., inhibiting SHBG production in the liver." (PMID 40281834, 2025). "Intriguingly, insulin signaling in the polycystic ovary, and potentially in other tissues, is selective." (PMID 40149685, 2025). "An enormous number of studies have shown that there is a link between insulin excess and hyperandrogenism, polycystic ovary syndrome (PCOS), ovarian follicle dysfunction, and endometrial hyperplasia." (PMID 40725728, 2025). "According to previous articles, orlistat can also decrease body weight and serum lipids and improve insulin sensitivity in obese females diagnosed with polycystic ovary syndrome." (PMID 39049073, 2024). "For example, previous research has demonstrated that insulin-sensitizing medications, such as metformin, can improve ovulation patterns, hyperandrogenemia, and metabolic health." (PMID 38524210, 2024).
polycystic ovary syndrome (continued). "It has been reported that circPUM1 is highly expressed in insulin-treated granulosa cells, and it promotes polycystic ovary syndrome progression by sponging miR-760." (PMID 38473814, 2024). "Both IR and hyperinsulinemia (excess insulin in the blood) are characteristic of metabolic syndrome and polycystic ovary syndrome (PCOS), two conditions that significantly affect reproductive capacity in women." (PMID 39444570, 2024). "We conducted a systematic review and meta-analysis on dairy consumption and its association with anthropometric measurements, blood glucose status, insulin levels, and testosterone levels in women with Polycystic Ovary Syndrome." (PMID 39421532, 2024). "PRX4 is also elevated in polycystic ovary syndrome, and it is negatively correlated with total oxidant status but positively correlated with insulin and HOMA-IR." (PMID 39765892, 2024). "Background/Objectives: Polycystic ovary syndrome is a common endocrine disorder in women of reproductive age characterized by insulin resistance and hormonal imbalances." (PMID 39599701, 2024). "Of note, high DHEA-S levels are observed in polycystic ovary syndrome, which is generally characterized by visceral fat accumulation and insulin resistance." (PMID 39377071, 2024). "In summary, n-3 PUFAs have the potential to ameliorate metabolic issues linked to polycystic ovary syndrome (PCOS), such as insulin sensitivity, lipid metabolism, and hormonal balance." (PMID 39275277, 2024). "Currently, endocrinologists and gynecologists show a huge clinical interest in inositol and its derivatives (especially D-chiro-inositol) since it can be used as an insulin sensitizer in the treatment of polycystic ovary syndrome (PCOS) and infertility." (PMID 39199391, 2024). "Disrupted insulin signaling in polycystic ovaries leads to increased androgen secretion, decreased synthesis of sex binding hormones, and increased free androgens." (PMID 39064282, 2024). "The most prevalent cause of oligo/amenorrhea in premenopausal females is polycystic ovarian syndrome (PCOS), and the majority of females with PCOS are insulin-resistant." (PMID 38021970, 2023). "A very early study by some members of our group showed that among 65 patients with identified polycystic ovarian syndrome, 71 percent were insulin resistant." (PMID 37200851, 2023). "In fact, a study involving women with polycystic ovary syndrome who practiced TRE from 1:00 PM to 9:00 PM (8 h) for 6 wk demonstrated a decrease in androgen levels, significant weight loss, and improved insulin sensitivity." (PMID 37635711, 2023). "We also summarized regulations of Metrnl in related metabolic diseases, including insulin sensitivity, polycystic ovarian syndrome, and diabetes." (PMID 36911663, 2023). "These parameters slightly impact differences in lipid profiles among studies since insulin is one of the main regulators of lipoprotein lipase activity, and hyperandrogenemia has an independent function in lipoprotein and lipid metabolism." (PMID 38024834, 2023). "The main endocrine disorders responsible for clinical manifestations are hyperandrogenemia and abnormal insulin response to glucose." (PMID 36829146, 2023). "The reduced insulin-mediated glucose disposal as a result of hyperandrogenemia was previously reported in both lean and obese insulin-resistant women with PCOS." (PMID 37371678, 2023). "On the other hand, studies confirm that following a low carbohydrate diet indicates improvements in waist circumference, fasting glucose and, serum insulin as well as weight in women with polycystic ovary syndrome." (PMID 37559131, 2023). "Studies indicate that insulin directly affects the production of androgens in polycystic ovary theca cells, and administering insulin can lead to elevated levels of LH and GnRH." (PMID 37710301, 2023). "Recent research has proven that women with polycystic ovary syndrome and persistent anovulation are the only ones who are insulin resistant." (PMID 36751233, 2023).